INS (insulin)
Diseases named in the same sentence as INS in open-access papers (continued):
Sharing a sentence is not in itself a finding about the gene and the disease.
diabetes (continued). "TyG emerged as a new force, which was shown to be superior to homeostasis model assessment-insulin resistance (HOMA-IR) in evaluating IR, especially for diabetes individuals receiving insulin therapy or without functioning beta cells." (PMID 37145256, 2024). "In summary, aggressively treating diabetes, if present, should contribute to the reversal of dementia; moreover, even if there is no diabetes, insulin resistance can be overcome through the use of intranasal insulin." (PMID 38542495, 2024). "Compared to the original treatment, the dose of basic insulin in diabetes patients did not change treated with SGLT-2i (WMD −0.27 [−0.58, 0.04], p = 0.086) and DPP-4i (WMD −4.95 [−11.18, 1.27], p = 0.119), respectively." (PMID 39072050, 2024). "After STZ treatment, these transgenic mice did not develop diabetes and maintained normal insulin and blood glucose levels." (PMID 39057094, 2024). "“One woman explained that she did not take insulin in front of her boyfriend's parents because diabetes was viewed as a defect, which was unacceptable” (T1DM, p2470)." (PMID 39574786, 2024). "Prediction by HOMA-IR and the Matsuda Index for the progression from Stage 1 to Stage 2, but not from Not Staged to Stage 1, suggests a greater impact of insulin sensitivity and insulin resistance when progression to diabetes is more advanced." (PMID 37914981, 2024). "Insulin pumps do not eliminate the need for human interaction or control while dealing with diabetes." (PMID 39065641, 2024). "Estrogen metabolites and certain dietary compounds may also activate TRPA1 to promote insulin secretion and GLP-1 release from intestinal L cells, which may be an appropriate method for diabetes management." (PMID 39273183, 2024). "Unlike microfluidic-based diagnosis and monitoring of diabetes, the use of microfluidics and related devices for insulin delivery is still largely in the preclinical stage." (PMID 38509342, 2024). "Diabetes is a serious condition in which glucose is unable to enter the cells, either because the pancreas does not secrete insulin sufficiently or insulin does not appropriately trigger the uptake of glucose." (PMID 39000868, 2024). "While current pharmaceutical options for diabetes management help control blood glucose levels they do not prevent, retard or reverse the decline in insulin-secreting β-cells." (PMID 39710778, 2024). "Chromium improves the glucose/insulin levels in subjects with hypoglycemia, hyperglycemia, and diabetes with no detectable effects on the control group." (PMID 38612580, 2024). "Adherence to the transition from oral agents to insulin injections in Type 2 Diabetes Mellitus therapy varies among patients and is not uniformly successful, leading to suboptimal glycemic control in certain cases." (PMID 38890763, 2024). "In the initial neonatal phase of 6q24-TND, SU use was not always successful in improving diabetes outcomes or allowing for cessation of insulin." (PMID 39025920, 2024). "They assist in monitoring parameters and complications of treatment, ensuring the maintenance of basal insulin to prevent reoccurrence of DKA, escalating difficult cases to the diabetes consultant, new insulin commencement, and safe discharge of patients after treatment." (PMID 38523875, 2024). "Moreover, in streptozotocin-induced diabetes models, SRG3 expression is decreased in eWAT, which can be reversed by insulin treatment." (PMID 39519233, 2024). "Despite the loss of glucose-stimulated islet electrical activity and Ca2+ entry, Kcnk16 L114P mice do not exhibit a drastic reduction in glucose-stimulated insulin secretion and overt diabetes." (PMID 38700926, 2024). "Diabetes mellitus (DM) represents a group of physiological dysfunctions characterized by hyperglycemia, resulting from insulin resistance (as seen in type 2 diabetes mellitus-T2DM), inadequate insulin secretion/production, or excessive glucagon secretion (in type 1 diabetes mellitus-T1DM)." (PMID 39070316, 2024).
diabetes (continued). "Diabetes mellitus is a chronic condition where the body cannot produce sufficient levels of insulin (type 1) or fails to effectively utilize the insulin it does produce (type 2)." (PMID 39684575, 2024). "Diabetes mellitus (DM) is a common clinical chronic disease with high rate of morbidity, long duration, and lifelong elevation of glucose levels, accompanied by insufficient secretion of insulin by pancreatic islet β-cells or insufficient biological effect of insulin in the peripheral tissues." (PMID 39247917, 2024). "The use of a combined treatment involving anti-CD6 therapy and oral insulin immunization effectively reverses recent-onset diabetes in non-obese diabetic mice." (PMID 39170074, 2024). "Diabetes is a chronic disorder that develops when the pancreas does not produce sufficient insulin (type 1) or when the body is unable to use the insulin it produces (type 2)." (PMID 39456481, 2024). "Among the 95 individuals with T2D (15.2%) who received insulin therapy beyond the first 6 months postdiagnosis, 30 (4.3% of the 626 individuals with T2D) did not have diabetes autoantibody titers measured." (PMID 38231515, 2024). "Japanese with type 2 diabetes, in whom insulin secretion capacity is mainly impaired during the development of diabetes, also have a decreased incretin effect compared to individuals without diabetes." (PMID 40607157, 2024). "It is especially important to accurately capture variation in insulin secretion for pre-diabetes because early dysfunction can be present without a profound change in glucose levels." (PMID 39013634, 2024). "Notably, the findings support the ITAS suitability in assessing PIR and identifying and addressing challenges in the timely initiation of insulin in T2DM patients, leading to improved diabetes management and patient outcomes." (PMID 39453515, 2024). "The cumulative incidence of thromboembolic events, including ischemic stroke/TIA/systemic embolism at 2 years, was similar in patients with non-insulin-treated diabetes and without diabetes (0.87%/year vs 0.86%/year; HR 1.02, 95% CI 0.70–1.47, p = 0.92)." (PMID 35976428, 2023). "The results in this study suggest that MB improves insulin sensitivity in diet-induced pre-diabetes even in the absence of diet intervention." (PMID 38096150, 2023). "The upregulation of PPAR-γ may highlight a new mechanism by which G0S2 helps improve insulin sensitivity in NAFLD and diabetes." (PMID 37033250, 2023). "Open-source automated insulin delivery (OS-AID) systems combine commercially available insulin pumps and continuous glucose monitors with open-source algorithms to automate insulin dosing for people with insulin-requiring diabetes." (PMID 37750308, 2023). "Pretreatment with GPR40 agonists enhanced the secretion of insulin in response to elevating blood glucose levels after glucose load in a diabetes model, but pretreatment with GPR120 agonist did not ameliorate postprandial hyperglycemia." (PMID 37583904, 2023). "Diabetes mellitus is a metabolic condition defined by persistent hyperglycemia in which insulin hormone activity on cell receptors is absent or inefficient, resulting in a substantial rise in blood glucose." (PMID 37240220, 2023). "Diabetes mellitus (DM) is a chronic disease that arises when the pancreas is not able to produce insulin or when cells do not make good use of insulin, a phenomenon that leads to elevated blood glucose levels (hyperglycaemia)." (PMID 37735655, 2023). "The patient’s mother and grandmother had diabetes that required insulin therapy, both were underweight with negative pancreatic antibodies." (PMID 37511676, 2023). "The type 2 diabetes mellitus (T2DM) is a group of metabolic diseases characterised by hyperglycaemia due to defects in insulin secretion, insulin action or both.With socio-economic development, T2DM has become an important public health issue affecting the health of the Chinese population." (PMID 37046317, 2023).
diabetes (continued). "Additionally, supplementing with vitamin D significantly improved fasting blood glucose, insulin, and HOMA-IR in patients with diabetes." (PMID 37764713, 2023). "In the present study, we selected db/db mouse, a model of type 2 diabetes as the research object, whose genetic background is C57BL/6 mouse diabetes gene knocked out and even insulin intervention fails to control hyperglycemia in db/db mouse." (PMID 36946337, 2023). "Insulin secretion in the ovine fetus is induced by glucose and amino acids, and hyperglycemia in macrosomic infants of diabetic mothers is accompanied by elevations in fetal insulin and, variably, IGF-1 (see discussion of Gestational Diabetes below)." (PMID 37764824, 2023). "Glucose effectiveness (Sg) is an insulin-independent mechanism that contributes to most of the whole-body glucose disposal after an oral glucose load in people without diabetes." (PMID 37367911, 2023). "The more common version of this metabolic disorder is type 2 diabetes mellitus (T2DM), described by increased insulin release to compensate for insulin resistance and progressive decline in islet secretory function within the pancreas, thus causing overall insulin deficiency." (PMID 36902074, 2023). "The underline mechanism by which elevated fasting SF levels pronounce diabetes, damage beta-cell function and decrease insulin sensitivity have not been fully illuminated." (PMID 37547304, 2023). "Type 2 diabetes mellitus (T2DM), characterized by elevated blood glucose, insulin resistance, and a relative lack of insulin, accounts for more than 90% of patients with diabetes." (PMID 37057310, 2023). "Moreover, the PCNA positive cell count was significantly higher in the insulin-, REO-, or combination-treated groups than in the diabetes group." (PMID 37016650, 2023). "In the increases in increases in the possibility of enhanced insulin sensitivity, as was also shown in a study investigating the effect of FK614 and pioglitazone, a thiazolidinedione PPARγ agonist in the Zucker fatty rat, an animal model for diabetes." (PMID 37893949, 2023). "Type 1 diabetes mellitus (T1DM) is a chronic condition in which the pancreas produces little or no insulin." (PMID 37193469, 2023). "The population was also divided into a “younger‐onset” group (diabetes diagnosis at < 30 years) and “older‐onset” group (diabetes diagnosis at ≥ 30 years), and further subdivided into participants “taking insulin” or “not taking insulin” (WESDR)." (PMID 36815723, 2023). "Data regarding duration of diabetes mellitus, dosage of insulin or other medication, or values of hemoglobin A1C were not captured in the BASKET-SMALL 2 trial." (PMID 36975883, 2023). "Diabetes is when the body does not produce enough insulin or cannot utilize the insulin it makes efficiently." (PMID 37570594, 2023). "Later scientists used a series of methods such as radioimmunoassay to prove the claim that lack of insulin sensitivity produces diabetes and proposed the basis of the corresponding mechanism." (PMID 37089923, 2023). "AST provides a measure of near-maximal insulin secretion (insulin secretory reserve), while BMTT is easy to administer and is more suitable in β-cell function assessment than OGTT for subjects who have confirmed diabetes." (PMID 36909323, 2023). "This may be related to the physical inconveniences of conventional insulin pumps, which have been reported to deter IPT acceptance and increase diabetes distress." (PMID 37814352, 2023). "Study included 69 insulin treated diabetes individuals and 36 non-insulin treated individuals in Ethiopia." (PMID 36778553, 2023). "In this study, food diaries and frozen blood samples were collected from the Baltimore Longitudinal Study of Aging (BLSA) participants, who underwent an oral glucose tolerance test (OGTT) and had no diabetes, and analyzed for glucose, insulin, and GIP levels." (PMID 38276259, 2023).
diabetes (continued). "Diabetes Mellitus (DM) is a chronic disease characterized by high blood glucose levels as a consequence of resistance or lack of insulin secretion from the pancreas." (PMID 36678609, 2023). "This section of the review enumerates the possible therapeutic mechanisms for AD of metformin, GLP-1 receptor agonists, DPP4 inhibitors, insulin, and SGLT2 inhibitors, all of which are widely applied to patients with diabetes according to official Clinical Guidelines." (PMID 36909158, 2023). "For the high frequency of these concomitant conditions, a recently published Endocrine Society’s guideline recommended the use of scheduled insulin therapy instead of noninsulin therapies for glycemic management in hospitalized subjects with diabetes." (PMID 36964858, 2023). "In addition, to describe diabetes through insulin resistance, T2DM is also characterized by a decrease in insulin secretion." (PMID 37434259, 2023). "While the GTT is no longer used as a mainstay in diabetes diagnosis, it continues to be used as an index of glucose excursion, which represents the balance of insulin sensitivity and beta cell function." (PMID 36967663, 2023). "This suggests that insulin and REGN647 might be targeting different signaling pathways that are altered with diabetes in skeletal muscle and trabecular bone, but similar pathways in cortical bone as their effect was not additive in this bone compartment." (PMID 38025035, 2023). "Hypoglycemia is a rare occurrence in individuals without diabetes but is common in sulfonylureas, glinides, or insulin-treated diabetes." (PMID 37925464, 2023). "Our studies reveal a novel role of UPRmt in suppressing insulin secretion and promoting apoptosis in mouse pancreatic β-cells, which could help better understand the etiology of IGT, prediabetes, and diabetes." (PMID 37758822, 2023). "So, if we can decrease the amount of PEDF in the circulation that may help to increase the insulin sensitivity, this makes PEDF a potential novel approach for the treatment of diabetes mellitus and other metabolic syndromes in the body." (PMID 36782201, 2023). "In Burkina Faso, because of limited access to insulin and high prices, most of young people with TID benefit from LFAC at the internal medicine department (the main referral center for diabetes in the country) of Yalgado Ouedraogo Teaching Hospital (CHU YO) in Ouagadougou." (PMID 37777715, 2023). "Although excessive daytime napping has been shown to be involved in diabetes occurrence, its impact on insulin secretion and sensitivity has not been elucidated." (PMID 38027100, 2023). "The World Health Organization’s global status report pertaining to noncommunicable diseases states that “Diabetes is a chronic disease, which occurs when the pancreas does not produce enough insulin or the body cannot effectively use the insulin it produces." (PMID 37621821, 2023). "The latest classification replaced the terms ‘insulin-dependent’ and ‘non-insulin-dependent’ diabetes, reflecting disease pathogenesis with the terms T1D and T2D." (PMID 37065759, 2023). "Insulin therapy can also have a significant negative impact on mental health, contributing to diabetes distress." (PMID 38077372, 2023). "Results were not separately given for patients with diabetes mellitus and for patients needing insulin." (PMID 36975883, 2023). "Type 2 diabetes mellitus (T2D) - is a condition that appears whenthe body produces inadequate amounts of insulin or the insulin that is produced does not function correctly to control blood glucoselevel." (PMID 37928486, 2023). "Various strategies have been proposed to realize diabetes remission, encompassing metabolic surgery, lifestyle intervention, insulin intensive therapy, and non-insulin hypoglycemic drugs." (PMID 38089622, 2023). "Insulin was less frequently used among people with type 2 diabetes who died by suicide, and not at all in people without a diagnosis of diabetes who died by suicide." (PMID 37840692, 2023).
diabetes (continued). "The triglyceride-glucose (TyG) index, which has superiority in assessing IR in both patients with and without diabetes and applicability to all subjects regardless of their status as recipients of insulin treatment, was created to get over this limitation." (PMID 37940979, 2023). "For example, pioglitazone, a potent insulin sensitizer, has been proven to reduce cardiovascular complications in patients without diabetes who had IR along with a recent history of ischemic stroke or transient ischemic attack." (PMID 37660027, 2023). "Most animals die within 30 weeks if proper insulin therapy is not given.Incidence of diabetes is shown only by 20% of animals.Patterns of serological or MLR reactivity are not affected by class II genes.The numbers of splenic lymphocytes are not significant." (PMID 36986591, 2023). "For instance, a study involving 277 Danish persons without diabetes found that the gut microbiota of insulin-resistant patients had an increased capacity to manufacture branched-chain amino acids (BCAAs) and elevated serum BCAA levels." (PMID 37834439, 2023). "This hypothesis has been fuelled by multiple reports of new diabetes in children and reports of excess DKA in newly diagnosed individuals, or indeed insulin-requiring hyperglycaemia." (PMID 36418578, 2023). "Hence, advanced techniques in diabetes care, including CGM, CSII, and new insulin preparations, can potentially allow better glycemic control in patients after TP." (PMID 36860372, 2023). "A positive association was identified between this insulin-based index and CKD progression in Korean adults without diabetes." (PMID 37255931, 2023). "While insulin was once the drug of choice for all forms of diabetes, the synthesis of non-insulin medications has made the use of insulin as a first- or even second-line treatment option nearly obsolete." (PMID 38192911, 2023). "Diabetes is a chronic disease characterised by elevated blood glucose levels resulting from either an absolute or relative lack of insulin or impaired insulin functionality." (PMID 37623239, 2023). "We postulate here that in diabetes, due to a lack of insulin, there is a decreased sodium re-absorption by the kidney." (PMID 37637592, 2023). "Here the authors report that THADA deficiency protects mice from hyperglycemia and glucose intolerance by promoting insulin secretion and inhibiting β-cell apoptosis, suggesting THADA could be explored as a potential therapeutic target for diabetes." (PMID 36823211, 2023). "Since extra-pancreatic insulin+ cells can partially compensate for lack of insulin in diabetes, it is very important to clear metabolic regulation of insulin expression." (PMID 38019818, 2023). "For example, evidence exists that the use of basal/bolus insulin strategies (rather than simply sliding scale insulin) for adult inpatients with insulin-dependent diabetes mellitus leads to better glycemic control." (PMID 37215538, 2023). "Because none of these children were diagnosed with diabetes at the time of blood sampling, and their insulin values were not outliers on logarithmic scale, their observations were included in the analytical sample." (PMID 37420130, 2023). "As MODY6 shows incomplete penetrance of diabetes, diet and oral hypoglycaemic agents tend to be effective management and insulin therapy is often not required." (PMID 37855645, 2023). "It has not been addressed in a similarly concerted way in insulin‐treated diabetes since genetically modified insulin analogues became widely used, although each of these analogues is antigenically distinct from native insulin." (PMID 37562398, 2023). "Compared with the common insulin dose during the TPN period for patients with diabetes, the higher ratio at 5.70 units of regular insulin per 10 g carbohydrate following TP might be attributed to complete insulin deficiency, postoperative stress, and the lack of basal insulin." (PMID 36860372, 2023).